CASP9 (caspase 9)
Diseases named in the same sentence as CASP9 in open-access papers (continued):
Sharing a sentence is not in itself a finding about the gene and the disease.
glioblastoma (42 papers, 2010 to 2025). The most malignant astrocytic tumor (WHO grade IV). "Apoptosis caused by XH (20 μM) in T98G human malignant glioblastoma cell line was driven by ROS generation, which mediated the triggering of the mitochondrial pathway with Casp-9 and Casp-3 activation." (PMID 31010128, 2019). "Brevilin A was reported to induce mitochondrial apoptosis in U87 glioblastoma cells and cause increased expression of cleaved caspase 9 and cleaved PARP." (PMID 31108969, 2019). "The results showed that Chr-A treatment caused a remarkably elevated ratio of caspase 9/caspase 9, as well as an elevated expression ratio of cleaved caspase 3/caspase 3, cleaved caspase 7/caspase 7 in glioblastoma cells of tumor tissues, which are executives downstream of the apoptotic process." (PMID 37367654, 2023). "The effect of garcinol on the activities of caspase-9 and caspase-3 was investigated on rat glioblastoma C6 cells." (PMID 38435669, 2024). "HnRNPA2/B1 also promoted AS through exon skipping in apoptotic enzyme caspase-9 (CASP9) and oncogene Ron to generate their respective cancer-promoting isoforms in glioblastoma cells." (PMID 36982162, 2023). "A significant increase in caspase 7 activity was noticed in anaplastic astrocytoma and glioblastoma multiforme cells after combination of both inhibitors, and this was correlated with caspase 9 activity enlargement." (PMID 38067099, 2023). "The results by mining TCGA database and immunohistochemistry also showed upregulation of caspase-9 mRNA and protein in human glioblastomas." (PMID 32210117, 2020). "Taken together, this study has shown the major roles of caspase-9 in transducing honokiol-induced mitochondria-dependent apoptosis in human drug-resistant glioblastoma cells." (PMID 32210117, 2020). "Differential expression of caspase-9 and -8 mRNAs in human normal brain tissues and glioblastomas were evaluated using the TCGA cohort." (PMID 32210117, 2020). "As a result, caspase-9 plays a major role in honokiol-induced apoptotic insults to human drug-resistant glioblastoma cells." (PMID 32210117, 2020). "Immunohistochemical analyses showed augmentation of caspase-9 in human glioblastomas compared to human meningioma tissues." (PMID 32210117, 2020). "It was reported that EV71 induces cell apoptosis through the mitochondrial pathway mediated by Caspase 9, viral protein synthesis is essential for the induction of apoptosis in human glioblastoma SF268 cells, and EV71 3 C triggers apoptosis in SF268 cells." (PMID 32434419, 2020). "The results by data mining in the cancer genome atlas (TCGA) database and immunohistochemistry displayed that expression of caspase-9 mRNA and protein in human glioblastomas was induced." (PMID 32210117, 2020). "Reduction of caspase-9 activity consequently repressed honokiol-induced DNA fragmentation and cell apoptosis in human drug-resistant U87-MG-R9 glioblastoma cells." (PMID 32210117, 2020). "Compared to normal brain tissues, expression of caspase-9 mRNA in human glioblastomas was upregulated by 21% (p < 0.05)." (PMID 32210117, 2020). "In comparison with caspase-8 activation, honokiol induced more 21%, 38%, and 44% stimulation of caspase-9 activity in human malignant drug-resistant glioblastoma cells." (PMID 32210117, 2020). "In this study, we showed that exposure to honokiol triggered more activation of caspase-9 than caspase-8 in human drug-resistant glioblastoma cells." (PMID 32210117, 2020). "In this study, we further showed a major role of caspase-9 in mediating honokiol-induced apoptotic insults to human drug-resistant glioblastoma cells." (PMID 32210117, 2020). "Exposure of human TMZ-resistant glioblastoma cells to 40 μM honokiol for 72 h led to a 3.1-fold elevation in the activity of caspase-9." (PMID 32210117, 2020). "Honokiol can kill human drug-resistant glioblastoma cells via an apoptotic pathway due to a main activation of caspase-9." (PMID 32210117, 2020).
glioblastoma (continued). "In contrast, exposure of human U87-MG-R9 glioblastoma cells to 40 μM honokiol for 24, 48, and 72 h led to significant 30%, 107%, and 160% increases in activity of caspase-9, respectively." (PMID 32210117, 2020). "Brevilin A was previously reported to induce mitochondrial apoptosis in U87 glioblastoma cells and induce increased expression of cleaved caspase 9 and cleaved PARP." (PMID 31178739, 2019). "MicroRNAs engage in regulating RNA molecules; however, only three miRNAs miR-24a, miR-582-5p, and miR-23a have been reported to regulate CASP9 function in colorectal or glioblastoma cells." (PMID 30886656, 2019). "In glioblastoma T98G cells, berberine inhibits the activity of Bcl-2, increasing the levels of Bax, caspase-9, and caspase-3." (PMID 30486451, 2018). "TRAIL induces apoptosis even when Bcl-2 is overexpressed in the tumor, since the former activates caspase-8, Bid, and caspase-9 in glioblastoma LN-229 cells when cultured with TRAIL." (PMID 30486451, 2018). "Glioblastoma cells treated with the compound-1H led to an elevation of apoptosis-related proteins (Bax, cleaved caspase-3, cleaved caspase-9 and cleaved PARP), while Bcl-2 was down-regulated in a dose-dependent manner." (PMID 29988358, 2018). "promotes human glioblastoma stem cell survival via direct inhibition of caspase 3, caspase 9, and Bim." (PMID 32309578, 2016). "Low expression of caspase 9 was confirmed also by Zarnescu and colleagues, who estimated the expression of caspase 9 in U-87 glioblastoma xenografts." (PMID 25852394, 2015). "Therefore, this study shows that honokiol can kill human TMZ-resistant glioblastoma cells via an apoptotic mechanism concurrently due to a main caspase-9-involved intrinsic pathway." (PMID 32210117, 2020). "In addition, levels of caspase-9 protein in human glioblastomas were enlarged compared to human meningioma tissues." (PMID 32210117, 2020). "In addition, our data mining in TCGA cohort further verified higher expression of caspase-9 mRNA in human glioblastomas." (PMID 32210117, 2020). "Interestingly, the expression of CASP9 was highly consistent across glioblastoma patients, with only one patient out of 181 exhibiting high CASP9 expression." (PMID 29113289, 2017). "However, Western blot showed that activation of caspase-9 by saponin 1 occurred as early as 12 h, and persistently increased at all time-points, in both of the glioblastoma cell lines." (PMID 24278406, 2013). "Furthermore, 5-Demethylnobiletin significantly induced glioblastoma cells apoptosis by upregulating the protein levels of Bax and downregulating the protein level of Bcl-2, subsequently increasing the expression of cleaved caspase-3 and cleaved caspase-9." (PMID 37139163, 2023). "Marizomib was found to induce caspase 9-dependent cell death in glioblastoma (GBM) cells and mouse models." (PMID 32033280, 2020). "Recent studies have shown that resveratrol induces the elevation of intracellular ROS by attenuating SOD2 and CAT expression and promoting the activity of caspase-9 and caspase-3, thereby remarkably arresting proliferation and triggering extensive apoptosis in glioblastoma multiforme (GBM) cells." (PMID 36558995, 2022). "To more closely examine the effects of UCMSC-CM on glioblastoma and the mechanisms by which UCMSC-CM induces apoptosis, we first examined caspase-9 and survivin mRNA levels in UCMSC-CM-treated T98G cells by qRT-PCR." (PMID 31908585, 2019).
glioblastoma (continued). "The compound-1H has the potential to induce apoptosis by up-regulating Bax, cleaved caspase-9, cleaved caspase-3, and cleaved PARP and down-regulating Bcl-2 protein levels in glioblastoma cells." (PMID 29988358, 2018). "We found that FK866 and CHS828, two distinct NAMPT inhibitors, increased the TMZ-induced apoptosis and necrosis, enhanced the TMZ-induced caspase-1, caspase-3, and caspase-9 activities, and augmented the TMZ-induced oxidative stress in glioblastoma cells." (PMID 28097126, 2016). "In vitro studies also show that Enzalutamide increases levels of caspase-9 and proapoptotic Bax protein in glioblastoma cells, amplifying cell death mechanism and thus not excluding a possible toxic effect on mitochondrial function." (PMID 40895111, 2025). "Qu induced cell death in glioblastoma U373MG cells through proteolytic activation of caspase-3 and caspase-7, a decrease in mitochondrial membrane potential and increases in caspase-3 and caspase-9 activities." (PMID 33192517, 2020). "Our previous study has shown that honokiol could stimulate cascade activations of caspase-9 and -3, G1 phase arrest, and cell apoptosis in human TMZ-sensitive glioblastoma cells." (PMID 32210117, 2020). "In the control groups, activities of caspase-8 and caspase-9 in human drug-resistant glioblastoma cells were not changed after treatment with DMSO for 24, 48, and 72 h." (PMID 32210117, 2020). "The transcriptional regulators of caspase-9 expression in glioblastoma cells have not yet been described." (PMID 31908585, 2019). "In tested glioblastoma cell lines expressing CB1 and CB2 cannabinoid receptors, both WIN55,212-2 and JWH133 disturbed the mitochondrial membrane potential and induced a subsequent cleavage of caspase 9 leading to the execution of apoptotic cell death using the same mitochondria-dependent pathway." (PMID 33499365, 2021). "We also verified by western blot analysis that the antiapoptotic protein Bcl-2 and total caspase-9 levels were decreased, while those of proapoptotic Bax and cleaved caspase-9 were increased by drug treatment, demonstrating that CYT387 could promote glioblastoma cell apoptosis." (PMID 34544426, 2021). "Immunoblotting procedures revealed that the glioblastoma cells exposed to 1 μM FC101 produced cleaved PARP protein expression, a marker of cells undergoing apoptosis, while no changes in caspase-9 protein expression, an initiator caspase, were observed." (PMID 25016928, 2014).
neuroblastoma (36 papers, 2002 to 2025). Neuroblastoma (NB) is the most common solid, extracranial childhood tumor. "Forty-four neuroblastoma primary tumours were analyzed by sequence analysis for mutations in the coding region of the CASP9 and DFFA genes, and in the promoter region of DFFA." (PMID 11870543, 2002). "By sequence analysis we detected four different polymorphisms in the CASP9 gene in neuroblastoma primary tumours." (PMID 11870543, 2002). "In vitro studies verified puerarin's impact on BIRC5, TIMP2, and CASP9 expression, inhibiting proliferation in neuroblastoma SH-SY5Y cells." (PMID 38982456, 2024). "In order to obtain the optimal results, multivariate COX regression analysis was performed on 6 key-target genes, and 3 genes associated with neuroblastoma were identified, i.e., BIRC5, TIMP2 and CASP9." (PMID 38982456, 2024). "Resveratrol administration, in conjunction with arsenic trioxide, has yielded benefits in neuroblastoma management, by regulating cellular viability and apoptosis, brought about by reduced levels of caspase-3 and caspase-9, as well as Bcl-2." (PMID 36672729, 2023). "Cytoplasmic PCNA is also associated with Caspase-9 in the SH-SY5Y neuroblastoma cell line, and S-nitrosylation of PCNA at the residues C81 and C162 decreases this interaction, leading to caspase-9 activation." (PMID 35677658, 2022). "Induction of apoptosis by MPP+ showed increases in caspase-9 protein expression in PC12 cells and caspase-9 cleavage in neuroblastoma cells." (PMID 28280525, 2017). "The current study demonstrated that triptolide not only induced neuroblastoma cell death and apoptosis via caspase-9/caspase-3 pathway activation, but also inhibited cell growth and viability by inducing cell cycle arrest at the S phase." (PMID 25354591, 2015). "We observed the expressions of caspase-3, caspase-8, and caspase-9 in the untreated SH-SY5Y neuroblastoma cells, which corroborated previous reports." (PMID 26664453, 2015). "TRD-induced apoptosis was reduced by inhibition of caspase-8 or caspase-9 in all four neuroblastoma cell lines respectively." (PMID 25568670, 2014). "Significant differences in caspase-dependency of TRD-mediated apoptosis would be expected in neuroblastoma if caspase-8 is activated subsequent to caspase-9 or vice versa." (PMID 25568670, 2014). "There, we have further demonstrated that Vpr-induced apoptosis in the SK-N-SH neuroblastoma cells through a mitochondria-dependent and caspase-9-mediated mechanism." (PMID 20628645, 2010). "In the present study we have examined two other genes in neuroblastoma primary tumours, CASP9 and DFFA." (PMID 11870543, 2002). "We conclude that although coding mutations of Caspase-9 and DFF45 are infrequent in neuroblastoma tumours, our discovery of a rare allele in two neuroblastoma cases should be taken to warrant further studies of the role of DFF45 in neuroblastoma genetics." (PMID 11870543, 2002). "The genes encoding Caspase-9 and DFF45 have both recently been mapped to chromosome region 1p36.2, that is a region alleged to involve one or several tumour suppressor genes in neuroblastoma tumours." (PMID 11870543, 2002). "Another study demonstrated that an opposite substitution (leucine with proline) in caspase-9 may lead to neuroblastoma development." (PMID 39062774, 2024). "Moreover, it increases the level of cleaved CASP3 and CASP9 in both neuroblastoma IMR-32 and NB-39 cell lines." (PMID 36497321, 2022). "In addition, caspase-4 acts upstream of caspase-9 in TM-induced apoptosis in human neuroblastoma SH-SY5Y cells." (PMID 32733636, 2020). "Furthermore, the treatment of neuroblastoma cells with the Naja naja atra cardiotoxin 3 has increased apoptosis via up-regulating caspase-9 and caspase-3." (PMID 33167431, 2020).
neuroblastoma (continued). "Pifithrin-α also significantly inhibited proteolytic activation of apoptotic factors such as caspase-9, caspase-3 and inactivation of PARP-1, providing a strong evidence for a functional association of Bex genes in neuroblastoma cell apoptosis mediated by curcumin." (PMID 28145533, 2017). "However, CS pretreatment significantly attenuated 6-hydroxydopamine-induced apoptotic signals, including imbalance of the Bcl-2/Bax ratio, release of cytochrome c, and activation of caspase-9 and caspase-3 in a human neuroblastoma cell line." (PMID 28617322, 2017). "Caspase-9 is a potential tumor suppressor in the childhood malignancy neuroblastoma." (PMID 25980443, 2015). "Hence, due to the completealteration in the structural property of the amino acid side chain, the stability ofthe protein is reduced which may affect the function of CASP9 protein, leading toderegulation of apoptosis and neuroblastoma development." (PMID 28324374, 2013). "In fact, treatment of neuroblastoma cells with LCA resulted in MOMP, which allowed the exit of cytochrome c, formation of the apoptosome and ultimately activation of caspase-9." (PMID 23940835, 2013). "Both caspase-9 and caspase-2 are well established initiator caspases for intrinsic apoptotic pathway suggesting for the first time that, MPTQ treated neuroblastoma cell death is mediated through only caspase-9 driven intrinsic apoptotic pathway." (PMID 23824039, 2013). "CASP9 is localized at 1p36.21, approximately 4 Mb proximal to our SRO-region, but still in the region commonly deleted by neuroblastoma tumours." (PMID 11870543, 2002). "Besides, multivariate COX regression analysis was carried out to obtain three genes related to the prognosis of neuroblastoma, namely BIRC5, TIMP2 and CASP9." (PMID 38982456, 2024). "Moreover, this compound induces apoptosis in SH-SY5Y neuroblastoma cells and promotes the expression of CASP3, CASP9 and CCNB (cyclin B), while decreasing the expression of CCND (cyclin D)." (PMID 36497321, 2022). "In this report, we observed consistent activation of caspase-9 in the form of a ∼35 kDa protein (cleaved caspase-9) but not caspase-2 in MPTQ treated neuroblastoma cells." (PMID 23824039, 2013). "Hence, the results of the nsSNP, rs1052574, for CASP9 gene which is predicted tohave a deleterious phenotypic effect and reduced protein stability may be consideredto be significant, reducing the function of the apoptotic protease cascade andthereby, leading to the development of neuroblastoma." (PMID 28324374, 2013). "Both the CASP9 (OMIM number 602234) and the DFFA (OMIM number 601882) genes have recently been localized to 1p36.2, a region commonly deleted in neuroblastoma tumours." (PMID 11870543, 2002).